EZH2 (enhancer of zeste 2 polycomb repressive complex 2 subunit)
Diseases named in the same sentence as EZH2 in open-access papers (continued):
Sharing a sentence is not in itself a finding about the gene and the disease.
colorectal cancer (continued). "DZNep (3-deazenplanocin A) which is a chemical inhibitor of S-adenosylhomocysteine hydrolase, suppresses histone methyltransferases including EZH2, and leads to marked reduction in cell proliferation and migration in colorectal cancer." (PMID 34901003, 2021). "After our previous work on the function of EZH2 in colitis, we conducted related studies on the function of EZH2 in colorectal cancer." (PMID 34671029, 2021). "Effect of inhibition of EZH2 on Deptor expression was confirmed in HCT116 colorectal carcinoma cells, in which interfering RNA treatment as well as a specific EZH2 inhibitor resulted in an increase in Deptor expression." (PMID 33412518, 2021). "Immunohistochemical interrogation of EZH2 has demonstrated correlation between high expression levels, adverse clinicopathologic features and worse survival in patients with colorectal cancer." (PMID 33050946, 2020). "MALAT1 also has been reported interaction with miR-218 decreasing E-cadherin and promoting oxaliplatin-based chemotherapy resistance in colorectal cancer through EZH2-mediating H3K27-me3." (PMID 32708561, 2020). "Another study suggests that lncRNA SNHG6 binds to EZH2 to methylate the tumor suppressor p21 promoter region and inhibit its expression, which proliferates colorectal cancer." (PMID 33050646, 2020). "Circ_0071589 facilitated the progression of colorectal cancer through enhancing the level of EZH2 through targeting miR-600." (PMID 33005174, 2020). "Tumor metastasis of colorectal cancer was promoted by the acceleration of the XIST/miR-137/EZH2 axis on cell migration and invasion." (PMID 32127028, 2020). "Particularly, downregulation of EZH2 was found as an epigenetic modulator of autophagy by regulating the mTOR pathway in the colorectal carcinoma." (PMID 33304896, 2020). "Significantly, SLC34A2-induced EZH2 overexpression promoted the proliferation and chemo-resistance to apoptosis in colorectal cancer (CRC) cells in vitro and in vivo." (PMID 30038060, 2019). "We aimed to simulate the observed EZH2 loss at the invasion front in human tumors by treating HCT116 colorectal cancer cells with the EZH2 inhibitor DZNep and transplanted 106 of these cells onto the CAM of 9-day old chicken embryos." (PMID 31317325, 2019). "Nevertheless, a study conducted in colorectal cancer cells has found that EZH2 promotes cell growth by directly binding to lncRNA SNHG1 without requiring mediation of miRNAs." (PMID 31695969, 2019). "The authors also showed that miRNA-101 was epigenetically silenced by OGT and EZH2 in several colorectal cancer cell lines resulting in the upregulation of the two enzymes in metastatic colorectal cancer in a vicious cycle fashion." (PMID 30873122, 2019). "In colorectal cancer, elevated expression of EZH2, BMI1, and SUZ12 in correlation with advances stages of the disease and poor prognosis has also been evidenced." (PMID 30873122, 2019). "lncRNA SNHG6 downregulates EZH2 expression by acting as a sponge for miR-26a/b and miR-214 in colorectal cancer." (PMID 31631065, 2019). "For example, as a member of Polycomb repressive complex 2 (PRC2), enhancer of zeste homolog 2 (EZH2) has been found to have a prominent function in colorectal cancer tumourigenesis." (PMID 31139021, 2019). "Inhibition EZH2 in colorectal cancer cells augmented CXCL9 and CXCL10 expression to affect the infiltration of effector T cells in tumor." (PMID 29556394, 2018). "Recent study showed that SPRY4-IT1 sponged miR-101-3p to promote proliferation and metastasis through upregulation of EZH2 in bladder cancer cells and colorectal cancer cells." (PMID 29489909, 2018). "We immunohistochemically evaluated EZH2 expression and assessed miR-31 and gene mutations [KRAS (codon 61/146), NRAS (codon 12/13/61), and BRAF (codon 600)] in 109 patients with colorectal cancer harboring KRAS (codon 12/13) wild-type." (PMID 28147317, 2017).
colorectal cancer (continued). "The polycomb group protein enhancer of zeste homolog 2 (EZH2) is a methyltransferase that suppresses microRNA-31 (miR-31) in various human malignancies including colorectal cancer." (PMID 28147317, 2017). "Further functional analysis is required for clarifying the regulatory role of EZH2 in the signaling pathway downstream of EGFR in colorectal cancer." (PMID 28147317, 2017). "Our current study showed a significant correlation between EZH2 expression and KRAS (codon 61/146) mutation in colorectal cancers." (PMID 28147317, 2017). "It has been shown that EzH2 down-regulation can reduce growth of invasive breast carcinoma, tumor angiogenesis, cell migration/invasion and metastasis in colorectal cancer cells." (PMID 29285251, 2017). "Low EZH2 expression was significantly associated with a shorter PFS and OS in patients with KRAS (codon 12/13) wild-type group colorectal cancer treated with anti-EGFR therapeutics." (PMID 28147317, 2017). "Immunohistochemistry for EZH2 expression were successfully performed in 109 (95%) colorectal cancers." (PMID 28147317, 2017). "In the result, low EZH2 expression was significantly associated with shorter PFS (log-rank test: P = 0.023) and OS (P = 0.036) in patients with colorectal cancer." (PMID 28147317, 2017). "MALAT1 is also associated with poor prognosis to oxaliplatin-based chemotherapy in colorectal cancer patients and promotes chemoresistance through EZH2." (PMID 29212230, 2017). "We performed a meta-analysis of 8 studies (n = 1059 patients) that evaluated the correlation between EZH2 overexpression and survival in patients with colorectal cancer." (PMID 29061982, 2017). "The role of the gene EZH2 in colorectal cancer survival is uncertainly, the aim of this study is clear this relationship." (PMID 29061982, 2017). "A meta-analysis was performed with elegible studies which quantitatively evaluated the relationship between EZH2 overexpression and survival of patients with colorectal cancer." (PMID 29061982, 2017). "MALAT1 is associated with poor response to oxaliplatin-based chemotherapy in colorectal cancer patients and promotes chemoresistance through EZH2." (PMID 29212230, 2017). "Using immunohistochemistry, we assessed 310 formalin-fixed paraffin-embedded (FFPE) specimens of colorectal cancer tissues in the EZH2 expression assay and successfully obtained 301 (97%) valid results." (PMID 26871294, 2016). "Our outcome in this study indicates that blocking expression of EZH2 would be an ideal strategy for combating colorectal cancer." (PMID 27706111, 2016). "Our previous study demonstrated that compared to normal tissues, colorectal cancer tissues expressed higher levels of EZH2." (PMID 27706111, 2016). "Our data also showed that high EZH2 expression was a favorable prognostic factor in colorectal cancer." (PMID 26871294, 2016). "Polycomb group protein enhancer of zeste homolog 2 (EZH2) is a methyltransferase that correlates with the regulation of invasion and metastasis and is overexpressed in human cancers such as colorectal cancer." (PMID 26871294, 2016). "A similar effect of EZH2 was observed in colorectal cancer, where targeting EZH2 in cancer cells augments the expression of CXCL9 and CXCL10 chemokines affecting the infiltration of the tumor by effector T cells." (PMID 27199994, 2016). "A similar effect of EZH2 was observed in colorectal cancer, where targeting EZH2 in cancer cells also augmented the expression of CXCL9 and CXCL10 chemokines, affecting the infiltration of the tumor by effector T cells." (PMID 27793053, 2016). "The influence of EZH2 expression on clinical outcomes was assessed in 299 patients with colorectal cancer (stages I–IV)." (PMID 26871294, 2016). "We therefore evaluated EZH2 expression using immunohistochemistry and assessed miR-31 and epigenetic alterations using 301 colorectal carcinomas and 207 premalignant lesions." (PMID 26871294, 2016).
colorectal cancer (continued). "The histone methyltransferase EZH2 is frequently over expressed in many tumour types including colorectal cancer (CRC)." (PMID 25549357, 2014). "In conclusion, we showed that combined expression of PcG proteins EZH2, BMI1 and SUZ12 and their associated histone modification H3K27me3 has prognostic value in our colorectal cancer study cohort." (PMID 25243792, 2014). "In this study, we investigated the expression of three PcG proteins (EZH2, BMI1 and SUZ12) and associated histone modification H3K27me3 in colorectal cancer tissues." (PMID 25243792, 2014). "In search for new biomarkers, we investigated the expression of Polycomb-group (PcG) proteins EZH2, BMI1 and SUZ12 and associated histone modification H3K27me3 in colorectal cancer." (PMID 25243792, 2014). "In the present work, we addressed this issue by analyzing EZH2 expression in colon cancer cells in vitro and in vivo, and by investigating the contribution of EZH2 to the growth of colorectal cancer cell lines." (PMID 21765901, 2011). "Enhancer of zeste homolog 2 (EZH2) is highly expressed in colorectal cancer stem-like cells." (PMID 39980929, 2025). "AKT3 expression decreased after treatment, indicating that controlling EZH2 activity might moderate colorectal cancer progression." (PMID 38672463, 2024). "Inhibitors of EZH2 can activate the expression of deubiquitinase USP22 in colorectal cancer via canonical epigenetic regulation through H3K27me3, thereby stabilizing PD‐L1 protein and enhancing its expression, inducing immune evasion and diminishing the anti‐tumor therapeutic efficacy." (PMID 38520088, 2024). "In addition, XIST binds to miR-137, and the enhancer of zeste homolog 2 (EZH2) is a target of miR-137 is repressed expression, which ultimately promotes tumor metastasis in colorectal cancer." (PMID 39830506, 2024). "Therefore, in this work, we investigated the role of EZH2 in the cellular effects of TKS4 deletion in colorectal carcinoma cells with the aim of better understanding the molecular networks relying on TKS4." (PMID 38672463, 2024). "Finally, using TCGA data, we found an inverse correlation between EZH2 expression and mean class II expression (R = −0.314, P = 0.00017) in pMMR colorectal cancer samples." (PMID 37565053, 2023). "It shows that EZH2 is capable of promoting colorectal carcinoma proliferation." (PMID 38048186, 2023). "It was shown in the consequences that EZH2 was in proportion to colorectal carcinoma cell invasion." (PMID 38048186, 2023). "In addition, we have verified the EZH2 function on the progression of colorectal carcinoma through nude mouse tumor-bearing experiments." (PMID 38048186, 2023). "Moreover, the lncRNA SNHG17/EZH2/p57 axis was reported to exhibit promoting effects on colorectal cancer progression." (PMID 35902569, 2022). "Also, a study has shown that LINC00114 serves as an oncogenic role in colorectal cancer (CRC) via regulating enhancer of zeste homolog 2 (EZH2)-mediated methylation of the target gene." (PMID 35414117, 2022). "Furthermore, therapeutic EZH2 inhibition by either 3-deazaadenosine A (DZNep) or genetic knockdown has been shown to induce autophagy and apoptosis in colorectal cancer cells in vitro." (PMID 35565249, 2022). "Interestingly, few studies found that EZH2 O-GlcNAcylation is required for EZH2 protein stability and enzymatic function in human breast and colorectal cancer cells." (PMID 35371030, 2022). "Additionally, microRNA-101-regulated OGT was found to promote EZH2 protein stability in colorectal cancer." (PMID 34462420, 2021). "In addition, down-regulating lncRNA ANCR regulates EZH2 expression and inhibits the invasion and migration of colorectal cancer." (PMID 34783641, 2021). "Moreover, EZH2 inhibition results in multitarget-mediated suppression of Hedgehog pathway, increases chemosensitivity and decreases self-renewal in colorectal cancer-initiating cells." (PMID 33743723, 2021).
colorectal cancer (continued). "Importantly, this study also found that EZH2 was an independent predictor of decreased overall survival in patients with colorectal cancer after multivariate analysis for lymph node and distant metastasis." (PMID 33050946, 2020). "Inhibition of EZH2, using siRNA or EZH2i DZNep, in colorectal cancer cells (RKO and HCT116), also increased LC3B-II levels and the expression of the ATG-related protein AMBRA1 (autophagy and BECLIN-1 regulator 1) and favored apoptosis but inhibited cell proliferation and migration." (PMID 31861179, 2019). "For example, SNHG1 affects colorectal cancer cell growth via regulation of EZH2 and miR-154-5p." (PMID 31615767, 2019). "However, the prognostic impact of high EZH2 expression is controversially discussed for colorectal cancer." (PMID 31317325, 2019). "A similar effect of EZH2 was also observed in colorectal cancer." (PMID 29556394, 2018). "Furthermore, EZH2 silencing partially impaired SNHG1 overexpression mediated proliferative capacity increase of colorectal cancer cells." (PMID 30266084, 2018). "Regarding colorectal cancer, we recently reported that EZH2 suppresses miR-31 expression by inducing histone H3 lysine 27 trimethylation (H3K27me3) on the miR-31 promoter and that EZH2 inhibition increased miR-31 expression." (PMID 28147317, 2017). "Therefore, further studies, both retrospective and prospective, are warranted in order to explore the expression of EZH2 as a biomarker for survival and to clarify the molecular mechanisms that involve EZH2 in colorectal cancer." (PMID 29061982, 2017). "Therefore, we conducted this study for assessing the relationship between EZH2 expression and clinical outcomes in patients with colorectal cancer treated with anti-EGFR therapeutics." (PMID 28147317, 2017). "In our research, we illustrated high abundance binding between BLACAT1 and EZH2 in colorectal cancer cells, and we further confirmed that BLACAT1 could mediate epigenetic regulation of p15." (PMID 28277544, 2017). "We further analyzed the association of EZH2 expression with the efficacy of anti-EGFR therapy in patients with colorectal cancer with no mutations in KRAS (codon 61/146), NRAS (codon 12/13/61), or BRAF (codon 600)." (PMID 28147317, 2017). "EZH2 overexpression indicates a better prognosis for colorectal cancer." (PMID 29061982, 2017). "Thus, our data suggest that EZH2 expression is a useful biomarker for anti-EGFR therapy in patients with colorectal cancer." (PMID 28147317, 2017). "EZH2 also mediates the silencing of the Disabled Homolog2-Interacting Protein (DAB2IP), which has been implicated in the regulation of EMT and metastatic potential in colorectal cancer and is a biomarker of good prognosis in medulloblastoma." (PMID 27793053, 2016). "Firstly, we didn’t investigate the effect of depletion of EZH2 on colorectal cancer in vivo." (PMID 27706111, 2016). "In addition we carried out the meta-analysis of high EZH2 expression and prognosis in breast, lung and colorectal cancer, respectively." (PMID 26683709, 2016). "In silico prediction has identified several potential miRNAs targeting EZH2 in colon cancer cells, and forced expression of hsa-miR-26a-5p and hsa-let7b-5p phenocopied the effects of EZH2 depletion in CRC cells, supporting a role of the two miRNAs in regulating EZH2 expression in colorectal cancer." (PMID 25611389, 2015). "In addition, siRNA-mediated knockdown of EZH2 exhibited profound effects on colorectal cancer cell growth in vitro." (PMID 25611389, 2015). "Using immunohistochemical staining (IHC) and semi-automated scoring, we studied the expression of PcG proteins EZH2, BMI1 and SUZ12 and their associated histone modification H3K27me3 in a cohort of 247 TNM stage I-III colorectal cancer patients, in correlation with clinical outcome." (PMID 25243792, 2014). "We studied EZH2 expression in 409 patients with colorectal cancer stages II and III." (PMID 19773751, 2009).
colorectal cancer (continued). "In colorectal cancer (CRC), EZH2 expression could also be linked to cancer stem cell potential." (PMID 31317325, 2019). "In addition, RNA pull-down assays also confirmed that SNHG1 could directly bound with EZH2 in colorectal cancer cells." (PMID 30266084, 2018). "However, most of these studies only focus on variants in the promoter region of EZH2, the association between missense variants in EZH2 and risk of colorectal cancer were not interrogated." (PMID 29212262, 2017). "Therefore, because of the relationship with miR-31, EZH2 may represent a new prognostic biomarker for molecular targeted therapies and can provide a promising therapeutic target in patients with colorectal cancer." (PMID 26871294, 2016). "We conclude that a subset of colorectal cancer patients may benefit from EZH2-targeting therapies." (PMID 27634879, 2016). "Hence, we suggest that EZH2 suppresses miR-31 expression in colorectal cancer and may correlate with differentiation and evolution of the serrated pathway." (PMID 26871294, 2016). "Furthermore, we performed functional analyses to identify whether EZH2 suppressed miR-31 expression in colorectal cancers." (PMID 26871294, 2016). "Here, it is found that squamocin effectively depletes both EZH2 and MYC in multiple cancer cell lines, including head and neck squamous cell carcinoma, and gastric and colorectal cancer, demonstrating potent efficacy in suppressing these in vivo tumor models." (PMID 39823459, 2025). "Colorectal cancer (CRC) is characterized by aggressive tumor growth and chemoresistance, with enhancer of zeste homolog 2 (EZH2) serving a pivotal role in these processes." (PMID 40314246, 2025). "It was also found that expression of EZH2 exhibited a strong positive correlation with dysfunctional T-cell phenotypes of KIRC, LUAD, BRCA-LumA, HNSC, myeloma, and colorectal cancer." (PMID 36545914, 2023). "With regards to EZH2 inhibition, low concentrations of GSK126 enhance the growth of some colorectal cancer organoids, an effect we confirm in a subset of the organoids in this dataset." (PMID 37565053, 2023). "According to the TIDE database, EZH2 expression showed a significant positive correlation with dysfunctional T-cell phenotypes of KIRC, LUAD, BRCA, HNSC, myeloma, and colorectal cancer." (PMID 36545914, 2023). "Currently, EZH2 and RUNX3 expression are discovered to be dysregulated in colorectal carcinoma tissues or cell strains." (PMID 38048186, 2023). "In colorectal cancer, emerging evidence has shown that PPARG signaling is downregulated due to the regulatory actions of EZH2 and HDAC1." (PMID 36142846, 2022). "Under the condition of colorectal cancer, long noncoding RNA PiHL epigenetically activated HMGA2 transcription by relieving EZH2 on HMGA2, thus promoting PI3K/AKT phosphorylation." (PMID 35264108, 2022). "In their cited work, the authors showed that the reduced levels of H3K27me3 achieved by EPZ-6438 EZH2 inhibitor promoted HCT116 and SW620 colorectal cancer cells’ resistance to oxaliplatin." (PMID 36230683, 2022). "In colorectal cancer cells, epigallocatechin-3-gallate, a polyphenol phytochemical, was discovered to inhibit the expression of Notch, BMI1, and EZH2 with an upregulation of the expression of miR-145, miR-34a, and miR-200c, thus reducing tumor growth." (PMID 36499676, 2022). "LncRNA CASC2 silences BCL2 expression through EZH2-dependent binding to the promoter region of BCL2, thus enhancing the cytotoxicity of berberine-induced colorectal cancer cells." (PMID 34888249, 2021). "In colorectal cancer, lncRNA HITT, in cooperation with Ezh2, inhibits HIF-1α transcription and inhibits hypoxia adaptation in colorectal cancer cells." (PMID 34888249, 2021). "For example, epigenetic repress E-cadherin expression by enhancer of zeste homolog 2 (EZH2) and histone deacetylases 6 (HDAC6), which are increased through Slug signaling that facilitating EMT and metastasis in colorectal cancer." (PMID 33406733, 2021).